SNORA80C (small nucleolar RNA, H/ACA box 80C)
Gene: Small nucleolar RNA gene on chromosome 16 (30,419,625 to 30,419,759, reverse strand). Ensembl gene ENSG00000199787.
Gene Ontology:
Biological process: RNA processing
Cellular component: nucleolus
Homologues: Orthologues: chimpanzee SNORA80C (99% identical), macaque SNORA80C (96% identical). Paralogues in human: SNORA80A (90% identical), SNORA80B (89% identical), SNORA80D (82% identical), SNORA80E (76% identical).